BNIP3 (BCL2 interacting protein 3)
Diseases named in the same sentence as BNIP3 in open-access papers (continued):
Sharing a sentence is not in itself a finding about the gene and the disease.
cancer (continued). "One of these modifications is H3K9me2, which is carried out by the methyltransferase EHMT2 that represses the transcription of LC3, WIPI1, DOR, and BNIP3 in cancer cells." (PMID 27174920, 2016). "In line with this, co-regulated BNIP3/CD47 mRNA expression is correlated to cancer progression and poor prognosis." (PMID 27896217, 2016). "In other cancers, including hematological malignancies and lung, gastric, pancreatic, and liver cancer, epigenetic silencing of BNIP3 expression as tumors progress to invasiveness and metastasis has been reported." (PMID 25810907, 2015). "Taken together, these experiments provide the evidence of feasibility for BMK1 inhibition in the setting of cancer stem cells through BNIP3 and BNIP3L." (PMID 26432836, 2015). "Second, T188 phosphorylation of endogenous BNIP3 was monitored in the same three carcinoma cell lines following exposure to hypoxia for 0, 6, 24, or 48 hr." (PMID 26102349, 2015). "First, A549, MDA-MB-231, and AU565 carcinoma cells, all of which express endogenous BNIP3, were subjected to nutrient deprivation for 0, 30, or 120 min." (PMID 26102349, 2015). "The famous hypoxamiR, miR-210, targets various genes, including BNIP-3, an anti-apoptotic gene that increases cancer cell proliferation and survival." (PMID 24914051, 2014). "These are the first studies to show activation of the Bnip3 death pathway by modulation of proton flux and its possible relevance to the treatment of breast and possibly other cancers." (PMID 24811485, 2014). "Altered HIF binding due to methylation changes in HREs has been further validated in additional target genes, such as BNIP3 or HIF1A, and is often associated with cancer progression." (PMID 23029193, 2012). "Epigenetic silencing of BNIP3 by promoter hypermethylation has been reported in several cancer types and contributes to resistance to hypoxia-induced cell death." (PMID 18728663, 2008). "Expression of BNIP3, which is induced by hypoxic stimuli, has been detected in several human cancer cell lines and cardiac myocytes subjected to hypoxia." (PMID 15756280, 2005). "Notably, genes including CAV1, ITGB1, BNIP3, and YTHDF2 were associated with the AKT signalling pathway, suggesting a functional link between ODC1 activity and cancer progression." (PMID 41803527, 2026). "In addition, IGF-1 signaling is crucial for sustaining cancer cell viability by stimulating mitochondrial biogenesis and mitophagy through the induction of BNIP3, thereby influencing therapy responses and cancer phenotype evolution." (PMID 41583513, 2026). "Therefore, we are convinced that targeting BNIP3‐driven mitophagy is a promising therapeutic approach for cancer treatment." (PMID 39945227, 2025). "Despite its pro-death activity, BNIP3 expression in cancer often predicts an aggressive disease." (PMID 40113750, 2025). "Moreover, it has been reported that cancer cells sustain hypoxia by upregulating the BCL2 interacting protein 3 (BNIP3)/BNIP3-like (BNIP3L), which in turn induces BECLIN-1 dependent autophagy by destabilizing Bcl-2-BECLIN-1 complex." (PMID 40917756, 2025). "Indeed, cancer cells sustain hypoxia by upregulating the BCL2 interacting protein 3 (BNIP3)/BNIP3-like (BNIP3L), which in turn induces Beclin-1 dependent autophagy by destabilizing Bcl-2-Beclin-1 complex." (PMID 40917756, 2025). "The role of the BH3-only protein BNIP3 in cancer is controversial." (PMID 40113750, 2025). "In addition, the potential of overexpression of BNIP3 to suppress cancer and promote autophagy has also been demonstrated in nude mice." (PMID 40837014, 2025). "At the same time, BNIP3 influences cancer progression as a target for various ncRNAs." (PMID 40028033, 2025). "Furthermore, many studies conducted on cancer cells have demonstrated that low pH increases BNIP3 stability in order to promote cancer survival in acidosis conditions." (PMID 38931477, 2024).
cancer (continued). "Furthermore, cancer cells with increased BNIP3/BNIP3L transcriptional activity exhibited CSC features, such as greater mammosphere-forming ability and high CD44 levels." (PMID 38834039, 2024). "Similarly, treatment with 3,4-dihydroxybenzyl alcohol in esophageal cancer cells activates mitochondrial autophagy due to high BNIP3 expression, ultimately resulting in cancer cell death." (PMID 39763653, 2024). "Finally, the different roles of BNIP3 in cancer and in host tissues require further investigation, as its function appears to be tissue-specific and varies across different tumors and molecular contexts." (PMID 39766033, 2024). "The 8 cell types were annotated based on the differentially expressed markers: Bnip3 for autophagic cancer cells, Mki67 for proliferating cancer cells, Cd14, Apoe, C1qc, Mrc1, Lyz2 for monocytes, Col3a1 for fibroblasts, Cd3e and Gzma for T cells, Flt1 for endothelial cells, and Klk1 for DCs." (PMID 38802348, 2024). "However, evidence from cancer patients with cachexia has been less clear in showing increased expression of MuRF1, MAFbx and BNIP3 in muscle, arguing for additional models and mechanisms of cancer-induced muscle wasting." (PMID 35319749, 2022). "To elucidate the mechanisms that confer resistance, we verified the expression of the mitophagic factor BNIP3 in both in vitro CDDP resistant models and cancer patients’ samples resistant to platinum-based chemotherapy, resulting in higher BNIP3 levels and enhanced mitophagy." (PMID 35459212, 2022). "The high ROS burden within BNIP3-positive cancer cells might explain the feedback activation of antioxidant transcription factor NRF2." (PMID 35912211, 2022). "We hypothesized that cancer cells might upregulate BNIP3 as a means to increase fitness when monolayer cell lines were converted into organoid lines." (PMID 35912211, 2022). "Up-regulation of BNIP3 has been reported to induce autophagy in cancer." (PMID 35200106, 2022). "BNIP3 expression is upregulated by hypoxia and in a variety of cancers." (PMID 35754840, 2022). "The inhibition of LINC00461 and BNIP3 alleviated the cancer-promoting effects of BNIP3." (PMID 35783530, 2022). "However, it is still unclear how the RNA expression level of BNIP3 dictates cell fate decisions of cancer cells at the single-cell level." (PMID 35912211, 2022). "While BNIP3 expression could be a new prognostic factor to predict the chemotherapy responsiveness of cancer patients, targeting mitophagy could be a new therapeutic approach to overcome platinum resistance." (PMID 35459212, 2022). "NRF2 pathway and metabolic reprogramming were among the enriched core modules, suggesting that cancer cells with higher expression of BNIP3 might have achieved increased fitness by multiple pathways." (PMID 35912211, 2022). "In almost all patients, scRNA-seq data revealed a cancer cell subpopulation with BNIP3 positivity." (PMID 35912211, 2022). "Despite some evidence implied autophagy in protecting cancer cells from the lethal effects of CDDP-induced DNA damage, and others linked BNIP3 proapoptotic role to cisplatin-induced cell death, the ultimate connection between these two processes has never been explored." (PMID 35459212, 2022). "Moreover, BNIP3 that is activated under hypoxic conditions has been shown to play a major role in mitophagy, which protects cancer cells from ROS, promoting cancer-cell survival." (PMID 34830491, 2021). "Thus, BNIP3 maintains the plasticity of the actin cytoskeleton, accounting for cell migration and cancer progression." (PMID 34568319, 2021). "The controversial role of BNIP3 in cancer could be explained by fact that its ability to induce cell death was inactivated." (PMID 33207677, 2020).
cancer (continued). "The controversial role of BNIP3 in cancer progression is not completely understood." (PMID 33207677, 2020). "Nuclear localization of BNIP3 may exclude its contribution to the regulation of mitochondria-dependent cell death, provoking cancer progression." (PMID 33207677, 2020). "The gene of BNIP3 in the AS we found can promote hypoxic survival and autophagy of cancer cells." (PMID 32617077, 2020). "Besides, up-regulation of BNIP3 has also been reported to accelerate cancer cell migration and invasion." (PMID 32587855, 2020). "The dual roles of BNIP3 in cancer progress and metastasis could be due to different interact with different factors through its Bcl-2 homology 3 (BH3) domain, also to the heterogeneity of different tumors." (PMID 32587855, 2020). "On one hand, suppression of autophagy by Atg gene knockdown could activate the BNIP3-mediated cancer cell death pathway after treatment with cisplatin." (PMID 32587855, 2020). "Furthermore, implication of BNIP3 in cancer progression appeared to be tissue-specific and depends on the molecular context and signaling pathways involved." (PMID 33207677, 2020). "Additionally, the inhibition of miR-181c in NRF2-silenced cancer cells restored BNIP3-mediated autophagy activation." (PMID 31078780, 2019). "Thus, Bnip3, depending on cancer cell type and hypoxic conditions, fulfills opposite functions in metastasis." (PMID 31921862, 2019). "Interestingly, overexpression of pro-apoptotic Bcl-2 family members, except Bnip3, frequently correlates with decreased metastasis and favorable outcomes in patients with various cancer types." (PMID 31921862, 2019). "Alterations in BNIP3 or PINK1 transcript levels are found in cachectic muscle of cancer patients as well as in mouse models, but whether and how they regulate mitophagy-induced cachexia remains to be further studied." (PMID 31121959, 2019). "Increased expressions of pro-apoptotic genes BNIP3, tumor necrosis factor related apoptosis-inducing ligand (TRAIL), and death-associated protein kinase 2 (DAPK2) have been reported to contribute to apoptosis induction in ceramide accumulation in cancer cells." (PMID 29546056, 2018). "Parkin recruitment also inhibit BNIP3, a protein that links apoptosis with mitophagy in cancer." (PMID 30344951, 2018). "In conclusion, expression of autophagy-related proteins (beclin-1, LC3B, p62, and BNIP3) was higher in HCNs and HCCs compared to FNs and HCAs, respectively, and this could have implications in cancer therapeutics." (PMID 28819333, 2017). "BNIP3 negative expression was significantly associated with an increased risk of cancer-related death." (PMID 28968982, 2017). "BNIP3 is considered a hypoxia-inducible proapoptotic member of the Bcl-2 family of proteins that has demonstrated differential expression in several types of cancer." (PMID 28968982, 2017). "To test whether mitophagy is involved in mitochondrial changes in cancer cells, we analyzed the mitophagy marker BNIP3 and found that its protein level was 7.9-fold elevated (p < 0.001) in MDA-MB-231 cells when it was compared with that in MCF-10A cells." (PMID 27746856, 2016). "To complement these data, we investigated the effects of docetaxel on the expression of HIF-1α target genes (Glut1, CA9, LDHA, and BNIP3) involved in the metabolism of cancer cells and pro-apoptotic genes (CASP3, CASP8, and CASP10) in siJNK2-transfected MDA-MB-231 cells under hypoxic conditions." (PMID 27263528, 2016). "In these examples, the increased PKA activity in solid tumors, which often tolerate nutrient deprivation and hypoxia, could protect BNIP3-expressing cancer cells from cell death in part by increasing phosphorylation of the BNIP3 C-terminus." (PMID 26102349, 2015). "As BNIP3 may represent a potential therapeutic target in cancer, it is important to understand how BNIP3 regulates mitochondrial function and autophagy." (PMID 25891311, 2015).
cancer (continued). "However, there are also many studies that showed that Bnip3 and Nix had a protective role and promoted cell survival in cancer cells." (PMID 22984526, 2012). "Although BNIP3 and TGM2 are associated with drug resistance and provide valuable prognostic markers in a variety of cancers, the expression and significance of BNIP3 and TGM2 have not been investigated in patients with laryngeal SCC receiving postoperative radiotherapy." (PMID 22458929, 2012). "However, it has been suggested that the ability of BNIP3 to induce cell death is blocked in cancer cells." (PMID 22458929, 2012). "Epigenetic alteration of BNIP3 is a frequent and cancer-specific event, which suggests that inactivation of BNIP3 likely plays a key role in the progression of some gastrointestinal cancers and that it may be a useful molecular target for therapy." (PMID 22827957, 2012). "Notably, BNIP3 may exert a dual role, as its overexpression has also been reported to induce cancer cell death under certain conditions." (PMID 40750884, 2025). "Zhang and co-authors found that overexpressing BNIP3 in dopaminergic cells can trigger oxidative stress and endoplasmic reticulum stress as it can dually localize to the mitochondria and endoplasmic reticulum, however these findings haven’t been confirmed in cancer cells." (PMID 39921807, 2025). "Similarly, deletions in BNIP3 genes and epigenetic silencing of BNIP3 promoters are also extensively documented in a number of cancers, such as breast, gastric, pancreatic, liver, lung, and hematological malignancies and are shown to be closely associated with chemoresistance and poor prognosis." (PMID 39201332, 2024). "BNIP3, an autophagy signaling protein (a pro-apoptotic member of Bcl-2), is expressed at high levels in colorectal and gastric epithelial cancers, suggesting that increased expression of BNIP3 may be necessary for the development of these cancers." (PMID 37666811, 2023). "We performed differential expression testing to found that cluster C3 over-expresses ENO1, BNIP3, PGK1 and LDHA, 4 genes associated with hypoxia (absolute log fold change above 0.5 and Wilcoxon test p-values below 0.01), that have been previously associated with cancer progression." (PMID 37917660, 2023). "It remains unclear how BNIP3 RNA level dictates cell fate decisions of cancer cells." (PMID 35912211, 2022). "Further, cachexic muscles of the C-26 mouse model displayed increased expression of Bnip3 and higher autophagic flux, suggesting that the autophagy–lysosome pathway might also play a role in muscle wasting during cancer-induced cachexia." (PMID 35319749, 2022). "Notably, Bnip3 (Bcl2 interacting protein 3) has been shown to regulate human microvascular EC death and overexpression of Naif1 (Nuclear apoptosis-inducing factor 1) has been reported to increase apoptosis of cancer cells." (PMID 34638535, 2021). "However, some studies have found that BNIP3 has an inhibitory effect on cancer." (PMID 33602168, 2021). "Additionally, BNIP3-induced mitophagy may play an important role in cancer cell survival after irradiation." (PMID 33207677, 2020). "However, degradation of Cav‐1 can increase autophagy markers, such as cathepsin B (active form), lysosomal‐associated membrane protein‐1, LC3B, beclin 1, autophagy‐related 16 like 1, (ATG16L1), and BCL2 interacting protein 3 (BNIP3), to increase autophagy of cancer cells." (PMID 32508059, 2020). "However, the role of BNIP3 in cancer metastasis is varied in different cancers." (PMID 32587855, 2020). "The elevated expression of the autophagy signature protein, BNIP3, a pro-apoptotic Bcl-2 member, has been demonstrated in colorectal and gastric epithelial carcinomas, suggesting that BNIP3 expression may be important for the development of these cancers." (PMID 31277291, 2019). "Additionally, other mitophagy-unrelated functions of BNIP3 and Parkin could play a role, depending on the cancer and type of stress considered." (PMID 31121959, 2019).
cancer (continued). "Furthermore, the expression of Bnip3 and Nix is commonly deregulated in cancer." (PMID 26611876, 2016). "Therefore, inhibition of BMK1 pathway suppressed cancer stem cells through BNIP3 and BNIP3L." (PMID 26432836, 2015). "However, some highly respiring cells and cancer cells tolerate BNIP3 expression, suggesting that a yet unknown mechanism exists to restrain the lethal effects of BNIP3 on mitochondria." (PMID 26102349, 2015). "Therefore we asked whether inhibition of the V-ATPase in cancer cells under hypoxic conditions supported a similar stabilization and accumulation of Bnip3 by conferring intracellular acidosis." (PMID 24811485, 2014). "In addition, Cathepsin-L, Gabarapl1 and Bnip3, which are known gene targets of FoxO in skeletal muscle involved in protein degradation through the lysosomal/autophagy pathway, were also identified as FoxO targets during cancer." (PMID 25539728, 2014). "Besides AIF and DR5, BNIP3 may bind to multiple promoters and alter gene expression in many different types of cancer cells." (PMID 23579274, 2013). "To consolidate our findings, we analyzed BNIP3 and EGFR, two alternative target genes of HIF-1 and HIF-2, respectively, which are relevant to cancer biology." (PMID 40918648, 2025). "Incomplete RFA triggers activation of autophagy, initiated via HIF-1α/BCL2 interacting protein 3 (BNIP3) and HGF/c-Met pathways—promotes residual cancer cell survival, accelerating post-treatment recurrence, proliferation, and invasiveness." (PMID 41438763, 2025). "As per the QPCR array data, Rapamycin is believed to induce apoptosis in cancer cells by altering the components of the extrinsic (CD40LG, DAPK1, LTA, TNFRSF21) and intrinsic (BIRC5, BNIP3) apoptotic pathways as well as the TP73 upstream modulator." (PMID 38276004, 2024). "Dysregulation of mitophagy-related proteins, such as FUNDC1, Parkin, BNIP3, BNIP3L/NIX, and p62/SQSTM1, has been shown to be correlated with cancer." (PMID 39524226, 2024). "As well-studied PINK1/Parkin-independent mitophagy receptor/adaptors, BNIP3 and BNIP3L/NIX have dual roles in cancer progression." (PMID 36831455, 2023). "Here, we discuss the roles that PINK1, Parkin, BNIP3, NIX, and FUNDC1 play in a wide array of cancers, clarifying the possible mechanisms of mitophagy in cancers." (PMID 36632220, 2023). "Both the BNIP3 and BNIP3L promoter regions contain CpG islands, and downregulation of BNIP3 and BNIP3L is always accompanied by promoter methylation in different cancer types." (PMID 37005657, 2023). "Except for the typical PINK1/Parkin pathway, BNIP3, NIX and other receptor pathways can mediate mitophagy, inhibiting many cancers." (PMID 37610095, 2023). "Furthermore, BNIP3 upregulated cancer cells might be armed with immune evasion arsenals." (PMID 35912211, 2022). "The function of the proteins overexpressed in cancer, such as CAIX, PDK, BNip3, Mxi-1, VEGF, and EPO, is regulated by HIF-1a in acute hypoxia." (PMID 36294785, 2022). "Immunohistochemistry and RNA expression analysis indicated that IDI1, BNIP3, IFRD1, and ZBTB10 were significantly differentially expressed in cancer and healthy tissues." (PMID 34226298, 2021). "Together, these results point to an inconsistent correlation between BNIP3 and HIF1 expression in several cancers." (PMID 33573362, 2021). "The function of BNIP3 is similar to that of PTP4A1, which includes the inhibition of cancer aggression." (PMID 34226298, 2021). "Although both BNIP3 and BNIP3L mediate hypoxia-induced mitophagy, the functional complementarity and differences of these two proteins in cancer-related mitophagy remain largely unclear." (PMID 33262988, 2020).